SKP2 (S-phase kinase associated protein 2)
Diseases named in the same sentence as SKP2 in open-access papers (continued):
Sharing a sentence is not in itself a finding about the gene and the disease.
prostate carcinoma (continued). "Taken together, these results provide a strong rationale that targeting Skp2 by FKB, its derivatives, or proteasome inhibitors (i.e. Bortezomib) should be evaluated as a novel approach for treatment of RB defective, castration resistant prostate cancer." (PMID 30885218, 2019). "Furthermore, the mRNAs of Skp2, RhoA, and SNAI1 were identified through q-PCR to be decreased in the DT-treated prostate cancer cells." (PMID 28157698, 2017). "FOXP3 has been shown to exert its growth inhibitory effect on breast and prostate cancer cells by transcriptionally repressing the expression of specific oncogenes (HER2, SKP2, SATB1 and MYC), and inducing the expression of specific tumor suppressor genes (CDKN1A, LATS2)." (PMID 24406338, 2014). "In addition, SKP2 interacts with pRB, PTEN, AR, and H-RAS in prostate cancer." (PMID 41542047, 2026). "Natural product 11 and 12 as non-covalent NAE inhibitors exhibit anti-prostate cancer effects via the degradation of Skp2, and natural product analogue 13 and natural product 14 are also identified as non-covalent NAE inhibitors by enzymatic and cellular assays." (PMID 37525282, 2023). "Treatment with MLN4924 has been shown to decrease Skp2 protein levels in prostate cancer cell lines PC3, PC3, DR12, and LAPC4 as well as decreasing Slug expression, indicating that neddylation blockade is a potential therapeutic approach for advanced prostate cancer." (PMID 37089937, 2023). "FKA treatments do not affect Skp2 expression at the transcriptional levels (data not shown), but down-regulates the protein expression of Skp2 and induces the accumulation of p27 protein, a Skp2 substrate, in prostate cancer cell lines in a dose and time manner." (PMID 26497688, 2015). "Therefore, the upregulation of p27Kip1 in USP19 depleted MCF10A cells appeared to be independent of KPC1, Skp2, or Pirh2 as was seen in most of the prostate cancer cell lines." (PMID 21264218, 2011). "Collectively, these findings suggest that targeting the AR NTD with ATRA and ralaniten may induce G1 arrest and senescence in prostate cancer cells that express AR-Vs, by a mechanism involving the Skp2/p27Kip1 pathway and Rb inactivation but not requiring p16INK4A." (PMID 33753863, 2021). "The roles of Skp2 in both EMT and cancer stem-like cells in prostate cancer have not been fully elucidated." (PMID 30952903, 2019). "However, unlike prostate cancer, treatment with FKA also leads to down-regulation of Skp2 mRNA, suggesting that FKA functions at a transcriptional level in osteosarcoma." (PMID 30250282, 2018).
lung cancer (49 papers, 2010 to 2026). A malignant neoplasm involving the lung. "On the other hand, FBXW2 also has been confirmed to inhibit the tumor growth and metastasis of lung cancer by promoting ubiquitylation and degradation of β-catenin and S phase kinase-associated protein 2 (SKP2)." (PMID 35499593, 2022). "FBXW2 suppresses proliferation and invasion of lung cancer cells by targeting S phase kinase-associated protein 2 (SKP2) and β-catenin." (PMID 35414786, 2022). "S-phase kinase-associated protein 2 (Skp2) is a member of F-box family, and its overexpression in lung cancer cells mediates their resistance to cisplatin chemotherapy." (PMID 33670518, 2021). "Our recent study identified FBXW2 as a tumor suppressor via promoting ubiquitylation of SKP2 (S phase kinase-associated protein 2) for targeted degradation to inhibit growth and survival of lung cancer cells." (PMID 30918250, 2019). "Because Skp2 is associated with the aggressiveness and proliferation of lung cancer, we also determined the effects of DT on lung cancer cell growth." (PMID 29207614, 2017). "In NSCLC, the chromosomal region including NDRG1 is consistently amplified and the gene over-expressed SGK1 can promote stem-like properties of lung cancer cells by preventing c-Myc degradation through ubiquitination operated by the S-phase kinase-associated protein 2 (Skp2)." (PMID 33266470, 2020). "We observed that amplification of SKP2 frequently occurs in various cancers, including sarcoma, urothelial or bladder cancer, lung cancer, gastric cancer, metastatic prostate cancer, and prostate adenocarcinoma with a range from about 12% to 6%." (PMID 41542047, 2026). "This interaction enhances SKP2 expression, which in turn stimulates aerobic glycolysis and proliferation of lung cancer cells, while suppressing apoptosis." (PMID 41241099, 2025). "Our research has revealed that the expression of SKP2 is increased in lung cancer tissues, and RPL35A is positively correlated with SKP2." (PMID 41241099, 2025). "Similar findings in lung cancer link increased Skp2 to enhanced metastasis and invasion via upregulation of MMP-2 and MMP-926." (PMID 39744562, 2025). "In lung cancer, small molecular inhibitors downregulated SKP2 and sensitized the lung cancer cells to paclitaxel." (PMID 38559562, 2024). "Eventually, a total of four genes including, CD151, MMP1, PVT1, and SKP2 genes were selected as reference genes based on their known functions in lung cancer progression and lymph node metastasis which have been pointed out in the found articles." (PMID 37185598, 2023). "Our recent study showed that FBXW2 was a tumor suppressor in lung cancer by promoting the ubiquitylation of SKP2 and β-catenin." (PMID 35499593, 2022). "FBXW2 is a poorly characterized F-box protein, as a tumor suppressor that inhibits growth and metastasis of lung cancer by promoting ubiquitylation and degradation of oncogenic proteins, including SKP2 and β-catenin." (PMID 35499593, 2022). "FBXW2 has been confirmed to promote ubiquitylation and degradation of oncogenic proteins, such as SKP2 and β-catenin, resulting in suppression of tumor growth and metastasis of lung cancer." (PMID 35499593, 2022). "As a tumor-promoting factor, miRNA-1297 reduces PTEN expression to activate Akt signaling, leading to Skp2 expression and the malignant behavior of lung cancer cells." (PMID 33670518, 2021). "Coupling opposite trend between Skp2 and p27 levels has been found in several cancer types, including hepatocellular carcinoma, gastric carcinoma, and lung cancer." (PMID 34068643, 2021). "Inhibition of Skp2 by SMIP004 sensitizes lung cancer cells to paclitaxel in A549 and NCI-H1975 cells." (PMID 34068643, 2021). "Though the SKP2 gene is commonly overexpressed in lung cancer, we can see that it is more overexpressed in current smokers than it is in nonsmokers." (PMID 32030321, 2020).
lung cancer (continued). "NDRG1 (N-myc downstream regulated gene 1) promotes stem-like properties via direct interaction with Skp2 and downregulation of Skp2 phosphorylation in nonsmall cell lung cancer." (PMID 30999935, 2019). "For example, miR-30 family postponed metastasis via targeting Skp2 in lung cancer cells in vitro and in vivo." (PMID 30847385, 2019). "Compared with normal tissues or cell lines, skp2 is found to be over-expressed in many different types of cancers, including lung cancer." (PMID 28036296, 2017). "Since Skp2 is firstly reported to be over-expressed in lung cancer, more and more studies have been involved to elucidate the role of Skp2 in lung cancer progression." (PMID 28036296, 2017). "6-OAP formed hydrogen bonds with Ser611/Ser613/Arg609 at the SH2 domain of STAT3 and inhibited the constitutive and interleukin-6-induced phosphorylated STAT3 (pSTAT3), leading to inhibitory effects on lung cancer cells and suppression of Skp2 transcription." (PMID 27835873, 2017). "A previous study demonstrated that Skp2 is a target of STAT3, and our previous work showed that Skp2 is dissociated from Skp1 and underwent proteolysis in lung cancer cells treated with 6-OAP." (PMID 27835873, 2017). "Based upon the biological functions of β-TrCP1, FBXW2 and SKP2 characterized in this study, we proposed an oncogene-tumour suppressor-oncogene axis in lung cancer cells." (PMID 28090088, 2017). "Targeting of Skp1 by a small compound 6-O-angeloylplenolin (6-OAP) results in dissociation and degradation of Skp2 and mitotic arrest of lung cancer cells." (PMID 27835873, 2017). "The upregulation of MMP-2 and MMP-9 is one of the mechanisms through which Skp2 promotes lung cancer cell invasion." (PMID 29207614, 2017). "Inactivation of STAT3 by 6-OAP also resulted in transcription suppression of Skp2, enhancing the inhibitory effect of 6-OAP on Skp2 to suppress lung cancer." (PMID 27835873, 2017). "E-cadherin, which is a key regulator mediating cell migration, is observed with a low expression in lung cancer and negatively regulated by Skp2." (PMID 28036296, 2017). "By western blotting and real time PCR assays, we found that YF-18 down-regulated Skp2 at both the protein and mRNA levels in a dose- and time-dependent manner in A549, H1975 and 95D lung cancer cells." (PMID 28036296, 2017). "Collectively, these results suggested that YF-18 inhibited lung cancer cell proliferation and migration through down-regulating Skp2." (PMID 28036296, 2017). "More important, previous studies showed down-regulation of Skp2 can induces apoptosis in lung cancer cells." (PMID 29207614, 2017). "In summary, we conclude that YF-18 inhibits cell growth, induces G2/M cell cycle arrest, and suppresses cell migration via down-regulating Skp2 in lung cancer cells." (PMID 28036296, 2017). "FBXW2 has tumour suppressor activity against lung cancer cells and blocks oncogenic function of both β-TrCP1 and SKP2." (PMID 28090088, 2017). "The increased expression of Skp2 has been shown in many different types of cancers, including lung cancer." (PMID 26942878, 2016). "We then analyzed the levels of SIRT2 and Skp2 in 6 commonly used lung cancer cell lines, compared to NT." (PMID 26942878, 2016). "Mechanistically, XPC deficiency has been reported to increase the invasiveness of lung cancer through downregulation of p27 (kip) and upregulation of skp2 and E2F1." (PMID 25871391, 2015). "The other genes AR, ATF2, CUL1, EP300, GATA4, LEF1, SKP2 in these subnetworks have also been identified as important in lung cancer." (PMID 24369052, 2013). "The interacting genes’ expression in the PLK1-MCM complex-SKP2 subnet of NSCLC patient datasets is weakly positively correlated or negatively correlated in normal samples but positively correlated in lung cancer samples." (PMID 22838965, 2012).
lung cancer (continued). "It has been reported that overexpression of Skp2 correlated with metastasis in different cancers including colorectal tumors, lung cancers, oral and esophageal squamous cell carcinoma, human gastric carcinoma and pancreatic ductal adenocarcinoma." (PMID 21386910, 2011). "To test this hypothesis, we generated a rescue model in which SKP2 was overexpressed in RPL35A-knockdown lung cancer cells." (PMID 41241099, 2025). "Together, these findings indicate that co-targeting RPL35A and SKP2 may represent a promising strategy to suppress aerobic glycolysis and mitigate malignant phenotypes in lung cancer cells." (PMID 41241099, 2025). "Other Skp2 substrate proteins might also play important roles in lung cancer other than p27, implying the multiple roles of Skp2 in cancer development." (PMID 37089937, 2023). "Furthermore, when treating lung cancers, different Skp2 targeting compound with respective effects should be selected according to the type, stage, pathological mechanisms of lung cancers." (PMID 37089937, 2023). "The β-TrCP-FBXW2-SKP2 signaling cascade forms the oncogene (β-TrCP1)-tumor suppressor gene (FBXW2)-oncogene (SKP2) axis that regulates the growth and survival of lung cancer cells via targeting each other for degradation, which is a process of crucial crosstalk among F-box proteins." (PMID 35414786, 2022). "FBXW2 inhibits proliferation of lung cancer cells by targeting SKP2 for degradation." (PMID 30918250, 2019). "Also, the wound healing and transwell assays results demonstrated that over-expression of Skp2 increased lung cancer cell migration in both YF-18 treatment and vehicle control and reversed cell migration inhibition by YF-18 treatment." (PMID 28036296, 2017). "Therefore, 6-OAP inhibited both Skp1 and STAT3 to repress Skp2, exhibiting inhibitory effects on lung cancer cell proliferation and survival." (PMID 27835873, 2017). "We examined the protein expression of Skp2 in DT-treated lung cancer cells." (PMID 29207614, 2017). "Skp2 is a vital protein in lung cancer metastasis and proliferation." (PMID 29207614, 2017). "It is reported that Skp2 plays an oncogenic role in the pathogenesis of lung cancer." (PMID 28036296, 2017). "Moreover, we also discovered 10–20 μM DT can inhibit the protein expression of Skp2 in lung cancer cells." (PMID 29207614, 2017). "Our results suggest that inhibiting Skp2 by YF-18 could be a potential effective approach to treat lung cancer." (PMID 28036296, 2017). "We transfected β-TrCP1, FBXW2 (wt versus mutant) and SKP2 alone or in various combinations into lung cancer cells and found that transfection of β-TrCP1 alone stimulated the monolayer growth and increased clonogenic survival of lung cancer cells." (PMID 28090088, 2017). "Given that 6-OAP is a Skp1 inhibitor, our data suggest that this compound may target Skp1 and STAT3 to suppress Skp2, augmenting its anti-lung cancer activity." (PMID 27835873, 2017). "Moreover, we found that lung cancer cell lines contained significantly higher levels of Skp2, compared to NT, shown by representative Western blots, and by quantification." (PMID 26942878, 2016). "In addition, miR-3163 as a mediator of Skp2 regulation inhibited cell growth in lung cancer." (PMID 30847385, 2019). "However, we do note that the relatively small number of Rb-defective TCLs from non-lung cancer histologies in these data sets might impair the ability to detect the Rb/SKP2 synthetic lethality." (PMID 29915391, 2018). "Our study established a previously unknown signalling cascade of the β-TrCP-FBXW2-SKP2 by forming the oncogene (β-TrCP)-tumour suppressor gene (FBXW2)-oncogene (SKP2) axis that regulates growth and survival of lung cancer cells via targeting each other for degradation." (PMID 28090088, 2017). "Nevertheless, whether Skp2 may be deacetylated by SIRT2 in lung cancer cells is unknown." (PMID 26942878, 2016).
lung cancer (continued). "Therefore, we hypothesized that PTEN, PI3K/AKT, and their corresponding intracellular interactors, p27 and Skp2, participate in thrombin-mediated lung cancer growth or metastasis." (PMID 25861627, 2015). "For instance, Skp2 is reported to promote the invasion via enhancing the expression of MMP-2 and MMP-9 in lung cancer oral squamous cell carcinoma." (PMID 41385185, 2025). "In summary, this study reveals that RPL35A is highly expressed in lung cancer and promotes SKP2 transcription by facilitating MYC nuclear translocation and enhancing its binding to the SKP2 promoter." (PMID 41241099, 2025). "In addition to this, according to previous studies, amplification of the SKP2 locus was reported in certain cancers, such as in lung cancer, biliary tract cancer, and glioblastoma, which may contribute to the upregulation of SKP2 in these cancers at transcriptional levels." (PMID 37308972, 2023). "6-OAP was also responsible for SKP2 inhibition by inhibiting STAT3 transcriptional activity, so it exerted anti-tumor activity in lung cancer cells." (PMID 35911641, 2022). "Skp2, a transcriptional target of STAT3, is a vital protein in lung cancer metastasis and proliferation." (PMID 29207614, 2017). "In summary, our data suggested that a low concentration (10 μM) of DT can block the phosphorylation of STAT3, the protein expression of Skp2, and the mRNA expression of STAT3 downstream genes to inhibit the migration ability of lung cancer cells." (PMID 29207614, 2017). "6-OAP inhibited tumor growth in SCID mice intravenously injected with lung cancer cells, and downregulated both STAT3 and Skp2 in tumor samples." (PMID 27835873, 2017). "We found that in contrast to oncogenic β-TrCP1 and SKP2, FBXW2 acts as a tumour suppressor to inhibit growth and survival of lung cancer cells, and high FBXW2 expression predicts a better patient survival." (PMID 28090088, 2017). "By defining FBXW2 as a substrate of β-TrCP1 and an E3 for SKP2, we established, for the first time, a signalling cascade of three F-box proteins β-TrCP-FBXW2-SKP2 in lung cancer cells." (PMID 28090088, 2017). "Recently, miR-340 was reported to directly target two important oncogenes, SKP2 and ROCK1, respectively in lung cancer and in osteosarcoma." (PMID 26799668, 2016). "Data obtained from microarrays, tissue samples from lung cancer patients and human lung cancer cell lines indicate that cell cycle regulatory molecules, like E2F1–5, p130, Skp2, cyclin D1 and p16, contribute to the growth and progression of lung tumors." (PMID 20421925, 2010). "Similarly, Skp2 also increases the expression of MMP-2 and MMP-9 to promote invasion of lung cancer cells." (PMID 41385185, 2025). "In addition, Skp2 activated PI3K/AKT pathway activities by upregulating the transcription activity of E2F, thereby potentially promoting the occurrence of lung cancer." (PMID 35321944, 2022). "Some reports in the literature also reported that miR-21-5p, miR-26-5p, and miR-30-5p could downregulate Skp2 in both MCF-7 and tamoxifen-resistant MCF-7 cells and miR-339 decreases Skp2 expression in lung cancer cell line A549." (PMID 34068643, 2021). "Among eight lung cancer cell lines and one immortalized line (BEAS-2B) tested, there is a general tendency of inversed protein levels between β-TrCP1 and FBXW2, as well as between FBXW2 and SKP2, whereas the mRNA levels among them are similar in all lines." (PMID 28090088, 2017). "Moreover, in several lung cancer cell lines, the SIRT2 levels significantly decreased and the Skp2 levels significantly increased." (PMID 26942878, 2016). "In addition, Skp2 overexpression induces the expression of matrix metalloproteinase (i.e. MMP-2, MMP-9) and invasion of lung cancer cells." (PMID 21386910, 2011). "Thus, our data on lung cancer cell lines are consistent with those from patients' specimens, suggesting that lung cancer cells may have decreased SIRT2 and increased Skp2." (PMID 26942878, 2016).
lung cancer (continued). "IHC staining of paired adjacent non-tumor and lung cancer tissue samples from patients showed markedly elevated expression of MYC and SKP2 in cancerous tissues." (PMID 41241099, 2025). "We then determined the effect of FBXW2 on SKP2 levels and found that the levels of endogenous SKP2 protein, but not mRNA were reduced upon FBXW2 transfection in lung cancer cells." (PMID 28090088, 2017). "While CDH1 depletion caused a minimal, if any, effect on the levels of SKP2 in two lung cancer cell lines, it did not affect FBXW2-induced SKP2 reduction at all." (PMID 28090088, 2017). "In a recent study, miR-340 was found to inhibit lung cancer cell proliferation and induce apoptosis by accumulating p27 protein through interfering the miR-221/222 interaction with p27 3′UTR, and by inducing the stabilization of p27 though targeting the key negative posttranslational regulator SKP2." (PMID 25831237, 2015).